RBM11 (RNA binding motif protein 11)
Description:
Tissue-specific splicing factor with potential implication in the regulation of alternative splicing during neuron and germ cell differentiation. Antagonizes SRSF1-mediated BCL-X splicing. May affect the choice of alternative 5' splice sites by binding to specific sequences in exons and antagonizing the SR protein SRSF1.
Tractability: No criterion of Open Targets' tractability assessment is met for any kind of drug.
Gene: Protein-coding gene on chromosome 21 (14,216,130 to 14,228,372, forward strand). Ensembl gene ENSG00000185272.
Subcellular location: Nucleus, nucleoplasm; Nucleus speckle
Subcellular location (Human Protein Atlas): Nucleoplasm
Gene Ontology:
Molecular function: poly(U) RNA binding; protein binding; protein homodimerization activity; single-stranded RNA binding; nucleic acid binding; RNA binding
Biological process: cellular response to oxidative stress; regulation of alternative mRNA splicing, via spliceosome
Cellular component: nuclear speck; nucleoplasm; nucleus
Genetic constraint (gnomAD): Loss-of-function variants: 20 observed, 22.71 expected, observed/expected ratio (o/e) 0.88, 90% interval 0.62 to 1.28. The upper end of that interval is the gene's LOEUF score, 1.28, which puts it in group 5 of 6, group 1 being the genes least tolerant of losing a copy. Missense variants: 285 observed, 311.36 expected, observed/expected ratio (o/e) 0.92, 90% interval 0.83 to 1.01. Synonymous variants: 120 observed, 110.92 expected, observed/expected ratio (o/e) 1.08, 90% interval 0.93 to 1.26.
Homologues: Orthologues: chimpanzee RBM11 (99% identical), macaque RBM11 (95% identical), pig RBM11 (75% identical), dog RBM11 (74% identical), guinea pig RBM11 (69% identical), mouse Rbm11 (68% identical), rat Rbm11 (60% identical), tropical clawed frog rbm11 (41% identical), Caenorhabditis elegans rbm-7 (20% identical), Drosophila melanogaster CG11454 (20% identical), zebrafish rbm11 (20% identical), Caenorhabditis elegans rnp-8 (19% identical). Paralogues in human: RBM7 (31% identical).
Diseases named in the same sentence as RBM11 in open-access papers:
RBM11 is named in the same sentence as 14 diseases in open-access papers, as found by Europe PMC text mining. Sharing a sentence is not in itself a finding about the gene and the disease. The quoted sentences say what the papers report.
glioblastoma (4 papers, 2021 to 2024). The most malignant astrocytic tumor (WHO grade IV). "It is previously reported that RBM11 protein was upregulated in glioblastoma tissues and promoted glioblastoma cell progression; however, the underlying mechanism for RBM11's oncogenic roles in cancer cells has not been defined." (PMID 34434291, 2021). "Research revealed that EVs containing RBM11 from glioblastoma cells induce oncogenic splicing in recipient cells, enhancing survival." (PMID 39132504, 2024). "On the one hand, apoptotic glioblastoma cells facilitate proliferation and therapeutic resistance of tumors by secreting apoVs with splice factor RBM11 to affect RNA splicing in recipient cells." (PMID 39872110, 2023). "Other examples include RBM39 in Acute Myeloid Leukemia or RBM11 in glioblastoma cells, among others." (PMID 34439272, 2021). "In agreement with the glioblastoma study, we also found that RBM11 was highly elevated in ovarian cancer tissues and positively regulated ovarian cancer growth and invasion." (PMID 34434291, 2021). "Nonetheless, the oncogenic roles of RBM11 in other cancer types beyond glioblastoma are needed to be further investigated." (PMID 34434291, 2021). "Recently, upregulation of RBM11 protein level has been observed in glioblastoma and RBM11 could promote glioblastoma cell proliferation and invasion in vitro and in vivo." (PMID 34434291, 2021). "Under pathological conditions, glioblastoma-derived apoVs inherit the splicing factor RNA-binding motif protein 11 (RBM11), which could be internalized in recipient cells to switch splicing of murine double minute 4 (MDM4) and Cyclin D1, triggering oncogene expression." (PMID 39872110, 2023).
ovarian carcinoma (2 papers, 2021). A malignant neoplasm originating from the surface ovarian epithelium. "In addition, a high level of RBM11 was associated with poor survival in ovarian cancer patients." (PMID 34434291, 2021). "RBM11 is elevated in ovarian cancer tissues and promotes ovarian cancer growth and invasion through activating the Akt/mTOR signaling pathway." (PMID 34434291, 2021). "Here, we studied the functions of RBM11 in ovarian cancer and found that RBM11 was overexpressed in ovarian cancer tissues and exerts oncogenic roles in ovarian cancer through activating Akt/mTOR signaling." (PMID 34434291, 2021). "To validate the oncogenic roles of RBM11 in ovarian cancer in vivo, we constructed a xenograft model using A2780 cells expressing control (ctrl) or RBM11 shRNA." (PMID 34434291, 2021). "Mechanically, we found that RBM11 positively regulated Akt/mTOR signaling pathway activation in ovarian cancer cells." (PMID 34434291, 2021). "Here, we found that RNA-binding motif protein 11 (RBM11) was highly elevated in ovarian cancer tissues compared with normal ovary, while RBM11 depletion in ovarian cancer cells resulted in impaired cell growth and invasion." (PMID 34434291, 2021). "RBM11 enhances ovarian cancer proliferation and invasion in vitro and in vivo, which highlighted the importance of RBPs in ovarian cancer progression." (PMID 34434291, 2021). "To further validate the RBM11 protein levels in ovarian cancer tissues, we performed Immunohistochemistry (IHC) staining and the result showed that RBM11 protein level was significantly overexpressed in ovarian cancer tissues compared with normal ovary." (PMID 34434291, 2021). "Moreover, knockdown of RBM11 also retarded tumor growth in the A2780 ovarian cancer xenograft model." (PMID 34434291, 2021). "RBM11 promotes ovarian cancer progression through stimulating Akt/mTOR signaling pathways." (PMID 34804951, 2021). "To explore the molecular mechanism by which RBM11 exerts its oncogenic function in ovarian cancer cells, we tested whether RBM11 could affect Akt signaling." (PMID 34434291, 2021). "In this study, we discovered a novel mechanism governing ovarian cancer progression through RBM11." (PMID 34434291, 2021). "In our present study, we investigated the function of RBM11 in ovarian cancers." (PMID 34434291, 2021). "To test the role of RBM11 in ovarian cancer progression, we knocked down RBM11 expression in ovarian cancer cells including OVCAR-3 and A2780 using two distinct shRNA targeting the RBM11 coding region." (PMID 34434291, 2021). "In the present study, we identified that RBM11 is especially expressed in ovarian cancer tissues, but not in normal ovary tissue, which demonstrates that RBM11 is a feasible target for drug design in future ovarian cancer treatment." (PMID 34434291, 2021).
bladder cancer (1 paper, 2026). "This study investigated the biological functions and molecular mechanisms of RNA-binding motif protein 11 (RBM11) in bladder cancer (BCa) progression." (PMID 41972004, 2026).
blood disease (1 paper, 2018). A disease that occurs in the blood. "The possibility that RBM11 modulates the splicing of CCND1, and an array of oncogenic genes in EWS, is consistent with known roles for related RNA binding proteins (RBM), including RBM10, RBM15 and RBM25, which alter gene splicing to promote various forms of blood disease and cancer." (PMID 30093970, 2018).
glioma (1 paper, 2022). A benign or malignant brain and spinal cord tumor that arises from glial cells (astrocytes, oligodendrocytes, ependymal cells). "Another mechanism of EV-mediated progression of glioma is the transfer of the RNA-binding motif 11 (RBM11), a pro-tumoral protein that promotes invasion and proliferation by apoptotic glioma cells." (PMID 36361947, 2022).
Intellectual disability (1 paper, 2016). "RBM11 was deleted in 10 out of 15 cases with the most severe phenotype (intellectual disability), whereas BTG3 in all of these cases." (PMID 27625702, 2016).
lung diseases (1 paper, 2022). "However, studies on RBM11 and ZNF14 in lung diseases are rare." (PMID 36523766, 2022).
neuroblastoma (1 paper, 2020). Neuroblastoma (NB) is the most common solid, extracranial childhood tumor. "For example, in the large SEQC cohort, RBM11, RBM20, RBMX2 were all upregulated in stage 4 neuroblastoma, compared to 4S with RBM47 being downregulated." (PMID 32707690, 2020).
cancer (5 papers, 2018 to 2021). A tumor composed of atypical neoplastic, often pleomorphic cells that invade other tissues. "We hypothesize that CYP4F22 overexpression may function to regulate the accumulation of pro-apoptotic sphingolipids (e.g. ceramide) in cancer cells, which similar to RBM11, promote alternative splicing of the BCL-XS splice variant." (PMID 30093970, 2018). "Furthermore, we demonstrated that RBM11 affected the Akt/mTOR signaling pathway, which provides evidence and explanation why RBM11 could promote cancer cell progression." (PMID 34434291, 2021). "Other RBM proteins family members also participate in promoting proliferation in various cancers, such as RBM5-AS1, RBM11, RBM15, RBM23, RBM33, etc.." (PMID 34804951, 2021). "While some members play the opposite role, promoting cell proliferation and the invasion of cancer, including RBM7, RBM11, and RBM15." (PMID 34804951, 2021). "It is also notable that we identified over 10 cancer-related genes (including PHGDH, CCND1, IGFBP-2, XAGE1B/E, CYP4F22, RBM11, ORAOV1, MDK, UGT3A5, SSX5, FBL, NKX2) potentially overexpressed in EFT tumors." (PMID 30093970, 2018). "While RBFOX3, RBM11 (RNA binding motif protein 11) and DDX25 (DEAD-box helicase 25) are generally downregulated in cancers compared to normal cells, the dysregulation of CELF5, ELAVL2 and ESRP1 is dependant on the type of cancer." (PMID 30704403, 2019). "Mechanistic insights are still required to explain the cytotoxic effects we observed, but the identification of RBM11, CYP4F22 and IGFBP-2 as new potential drug targets for EFT would seem to confirm the utility of this open source, computational methodology for cancer drug discovery." (PMID 30093970, 2018). "This transcriptome profiling approach is highly effective for cancer drug discovery, as it identified new EWS-specific target genes (e.g. CYP4F22, RBM11 and IGBP-2), and predicted effective antisense agents (EC50 < 1 μM) that demonstrate both synergy and antagonism in combination therapy." (PMID 30093970, 2018).
tumor (4 papers, 2021 to 2026). "Integrated bioinformatics analysis of the TCGA database and validation in clinical tissues revealed that RBM11 is significantly upregulated in BCa and positively correlated with advanced tumor stage, poor prognosis, and epithelial-mesenchymal transition (EMT)." (PMID 41972004, 2026). "Apoptotic vesicles released from dying cells promote proliferation, migration, and therapy resistance in adjacent surviving tumor cells through multiple signaling pathways, potentially involving RBM11-mediated splicing regulation." (PMID 40747304, 2025). "RBM11 is markedly overexpressed in tumor cells following therapy and dissociates from dying cells within ApoBDs." (PMID 40747304, 2025). "Consistent with in vitro results, we found that knockdown of RBM11 significantly inhibited tumor growth in the A2780 xenograft model." (PMID 34434291, 2021). "Upon co‐uptake into recipient cells with apoptotic vesicles, RBM11 re‐splices MDM4 and cyclin D1 transcripts to generate isoforms with enhanced oncogenic potential, thereby augmenting the proliferative and resistant phenotype of post‐treatment tumor cells." (PMID 40747304, 2025).
RBM11 also shares sentences with these, for which no sentence is quoted: acute myeloid leukemia (1 paper); colon cancer (1); Down syndrome (1); Obesity (1).